IL6 (interleukin 6)
Diseases named in the same sentence as IL6 in open-access papers (continued):
Sharing a sentence is not in itself a finding about the gene and the disease.
colon adenoma (6 papers, 2011 to 2025). An adenoma that arises from the colon. "In the entire study population, IL-6 level is positively associated with risk of colon adenomas (P-trend = 0.002) in crude analysis; however this association is reduced to non-significance with adjustment for covariates (P-trend = 0.10)." (PMID 24235998, 2013). "This suggests that elevated Il-6 is likely associated with essential colonic processes: epithelial proliferation, infection prevention, and wound healing following resolution of colonic adenomas in response VAX014 treatment." (PMID 37373142, 2023). "Our study is also the first to examine haplotype-tagging SNPs as well as circulating levels of IL-6 and TNF-α and risk of colon adenomas in Caucasians and African Americans separately." (PMID 24235998, 2013). "We also evaluated the association of SNPs in the IL6 and TNF-α genes and colon adenomas." (PMID 24235998, 2013). "We investigated the associations between circulating levels and genetic variants of IL-6 and TNF-α and colon adenomas in a case-control study including 894 Caucasians and 557 African Americans who underwent routine colonoscopy at University Hospitals Case Medical Center, Cleveland, Ohio." (PMID 24235998, 2013). "We sought to determine whether circulating levels of IL-6 and TNF-α, or genetic polymorphisms in IL-6and TNF-α were associated with colon adenoma and if so, whether that association differed by race." (PMID 24235998, 2013). "Specifically in this study we sought to determine whether inflammation, as measured by inflammatory cytokines IL-6 and TNF-α, exhibited similar associations with colon adenomas in both Caucasians and African Americans in our study." (PMID 24235998, 2013). "Our results do not support pre-diagnostic levels of IL-6, TNF-α or their genetic variants as significant risk factors for the development of colon adenoma." (PMID 24235998, 2013).
complex regional pain syndrome (6 papers, 2012 to 2025). A chronic pain syndrome characterized by a disproportionate spontaneous or stimulus-induced pain, accompanied by a variably mixed myriad of autonomic and motor disorders including symptoms such as swelling, allodynia, skin blood supply and trophic disturbances. "Clinical studies have reported elevated IL-6 levels in the CSF in various pain-related neuropathological situations, including complex regional pain syndrome and lumbar radiculopathy." (PMID 38419042, 2024). "CSF IL-6 is increased in the complex regional pain syndrome and radiculopathy, and serum IL-6 is increased in FM." (PMID 22776095, 2012). "For instance, IL-6 is elevated in cerebrospinal fluid (CSF) of patients with complex regional pain syndrome (CRPS) and elevated IL-8 in patients with fibromyalgia." (PMID 32213162, 2020).
congenital heart disease (6 papers, 2007 to 2025). A heart disease that is present at birth. "As previously reported, we detected significantly elevated levels of serum IL-6, IL-8, and IL-10 at all post-operative timepoints investigated (T1–T3) in patients with congenital heart defects undergoing cardiac surgery involving CPB." (PMID 39596461, 2024). "The aim of the present study is to investigate the ghrelin in congenital heart disease and the association of ghrelin with TNF-α and IL-6.Materials and methods." (PMID 18274638, 2007). "We measured serum ghrelin, TNF-α, and IL-6 levels using spesific immunoassay in 68 patients (47 acyanotic, 21 cyanotic with congenital heart disease) and in 25 control subjects.Results." (PMID 18274638, 2007). "The objective of this study is to investigate and compare the functional role of ghrelin on the regulation of energy balance in children with cyanotic and acyanotic congenital heart disease and the association of ghrelin with TNF-α, IL-6, that were not entirely confirmed in literature by now." (PMID 18274638, 2007).
craniopharyngioma (6 papers, 2019 to 2025). A benign, partly cystic, epithelial tumor of the sellar region, presumably derived from Rathke pouch epithelium. "Evidence from our group and others has shown that the cystic and solid tumor components of craniopharyngioma have high levels of IL-6R and IL-6, providing a potential target for therapy." (PMID 31497533, 2019). "Notably, we observed upregulation of IFNγ, IL-1, IL-6, and TNFα in craniopharyngiomas, tumors difficult to resect due to their anatomical location and critical surrounding structures." (PMID 37492101, 2023). "The mechanism of TAM recruitment and differentiation in pediatric craniopharyngiomas may be attributed to both the IL-8 and IL-6 cytokines." (PMID 37509316, 2023). "In adamantinomatous craniopharyngioma, numerous clinical trials to explore MEK, PD-1, WNT, and IL-6 inhibition are currently active." (PMID 40042714, 2025). "With the recent advances in precision medicine, some potential targets such as IL-6, PD1/PD-L1, MEK, IDO-1, and others have been identified for the treatment of craniopharyngioma." (PMID 39050573, 2024). "Despite these advancements in the management of papillary craniopharyngiomas, limited progress has been made in the management of adamantinomatous craniopharyngiomas, where a range of different molecular therapies have been employed (anti-EGFR, anti-IL6 and anti-VEGF) with heterogenous results." (PMID 39456573, 2024).
cryopyrin-associated periodic syndrome (6 papers, 2014 to 2025). Cryopyrin associated periodic syndrome (CAPS) defines a group of autoinflammatory diseases, characterized by recurrent episodes of systemic inflammatory attacks in the absence of infection or autoimmune disease. "There are currently several Food and Drug Administration (FDA) approved TNF-α, IL-1 and IL-6 inhibitors for clinical indications such as rheumatic diseases, Crohn's disease and cryopyrin-associated periodic syndromes (CAPS)." (PMID 33050789, 2020). "In vivo, neutralization of excessive IL-1β in cryopyrinopathies and in deficiency of interleukin-1 receptor antagonist (DIRA) results in decrease in IL-6 production." (PMID 25061439, 2014). "Serum IL-6 levels are elevated in humans and mice, with NLRP3 inflammasome-mediated diseases, such as cryopyrin-associated periodic syndromes (CAPS), a disease caused by mutations in the Nlrp3 gene." (PMID 39982672, 2025). "Cryopyrin-associated periodic syndromes (CAPS) are caused by a mutation in NLRP3 inflammasome, resulting in increased IL-1β and IL-18 production, but impaired production of the anti-inflammatory IL-6 and IL-1RA cytokines." (PMID 29515591, 2018).
cutaneous leishmaniasis (6 papers, 2016 to 2024). Leishmaniasis affecting the skin. "We now show that IL-6 production by eosinophils was higher in DCL patients as compared to LCL patients, suggesting that IL-6 plays a role in disease severity in cutaneous leishmaniasis." (PMID 38359037, 2024).
cysticercosis (6 papers, 2011 to 2023). "In addition, it is known that IL-5 and IL-6 participate in the recruitment of eosinophils, which are considered important effectors in the destruction of parasites in porcine cysticercosis." (PMID 37242348, 2023). "Increased IL6 levels during murine chronic cysticercosis induce a feminization phenotype." (PMID 34075113, 2021). "Here, we show that microglia display a diminished expression of M1-inflammatory mediators such as tumor necrosis factor-alpha (TNF-α), interleukin-6 (IL-6), and nitric oxide synthase 2 (NOS2) in murine neurocysticercosis." (PMID 26148848, 2015). "In early stages of experimental cysticercosis a clear but transient Th1-type immune response develops (high levels of IL-2 and IFN-γ), but as infection time progresses a permanent Th2-type response follows (high levels of IL-4, IL-6 and IL-10)." (PMID 21912714, 2011). "The immunopathology of T. crassiceps cysticercosis in mice is that of an initial non-permissive Th1 type, which shifts to a parasite permissive Th2 type during chronic stage of infection and is accompanied by an increase in IL-4, IL-6 and IL-10 cytokines." (PMID 22206032, 2011). "However, no IL-6 and TNF-α secretion was detected after murine microglia were grown in the medium containing soluble factors from Mesocestoides corti metacestodes which are used as a murine model for neurocysticercosis." (PMID 27842570, 2016).
duodenal ulcer (6 papers, 2016 to 2022). An ulcer in the duodenal wall. "Moreover, an increase in IL-6 in association with H. pylori pathogenicity and other peptic and duodenal ulcers has also been reported." (PMID 32256476, 2020). "Furthermore, it was shown that gastric epithelium significantly contributed to the antral IL-1β and IL-6 response from H. pylori-infected duodenal ulcer patients and asymptomatic carriers." (PMID 31065302, 2019).
gram-positive bacterial infections (6 papers, 2013 to 2025). Infections caused by bacteria that retain the crystal violet stain (positive) when treated by the gram-staining method. "In contrast, IL-6 production following Gram-positive bacterial infections was much lower." (PMID 40873569, 2025). "Pla2g2d also known as the “resolving sPLA2” ameliorates inflammation through mobilizing proresolving lipid mediators and reducing Th1 cytokine production, while Pla2g2a can be stimulated by IL-6 production and protects against Gram-positive bacterial infection." (PMID 34295313, 2021). "Interestingly, IL-6 and IL-10 can help distinguish between Gram-negative and Gram-positive bacterial infections." (PMID 36590299, 2022). "In contrast, the expression of IL-6 and RNAse7 was dependent on the presence of MRSA, while previously it was reported that RNAse7 expression was not induced by a gram-positive bacterial infection (e.g. with S. aureus)." (PMID 24340061, 2013).
hemangioma (6 papers, 2013 to 2025). A benign vascular lesion characterized by the formation of capillary-sized or cavernous vascular channels. "Bleeding and necrosis associated with a large hemangioma appear to trigger the release of damage-associated molecular patterns, stimulating interleukin 6 production, promoting prostaglandin E2 synthesis, and ultimately leading to fever." (PMID 40404957, 2025). "High levels of IL-6 have also been found in infantile hemangioma, and inhibition of IL-6 was shown to reduce hemangioma growth." (PMID 36902129, 2023). "For example, in human hemangioma and angiosarcoma lesions, high levels of RelA and strong activation of the NF-λB/IL-6/STAT3 signaling axis has been previously reported." (PMID 27105514, 2016). "HIF-1α could inhibit VEGFA expression, whereas VEGF-mediated upregulation of IL-6 triggers the progression of hemangioma cells." (PMID 31949494, 2020). "However, IL-6, IL-1β, and IFN-β protein levels in the three clinical samples with hemangiomas were dramatically increased compared to the healthy samples." (PMID 27252695, 2016).
Hemophagocytosis (6 papers, 2014 to 2025). Phagocytosis by macrophages of erythrocytes, leukocytes, platelets, and their precursors in bone marrow and other tissues. "Additionally, they displayed systemic autoinflammation marked by elevated levels of IL-1β, IL-18, and IL-6, alongside cytopenia and hemophagocytosis." (PMID 41116055, 2025). "Activated immune cells have been established to release proinflammatory cytokines (IFN-γ, TNF-α, IL-1, IL-6, TNF-α, and so on), leading to high levels of macrophage activation, which, in turn, might cause hemophagocytosis, tissue damage, organ failure, and other inflammatory manifestations." (PMID 41020231, 2025).
Hyperkalemia (6 papers, 2013 to 2025). An abnormally increased potassium concentration in the blood. "Thus, metabolic acidosis and hyperkalemia were relieved after treating rhabdomyolysis rats with procainamide, indicating that procainamide has beneficial effects on the mitigation of plasma IL-6 levels and muscle injury." (PMID 26918767, 2016).
hypersomnia (6 papers, 2019 to 2025). A sleep disorder characterized by excessive sleepiness. "In particular, both higher CRP and IL-6 showed converging associations with hypersomnia (CRP OR = 1.27, 95% CI = 1.13–1.43; IL-6 OR = 1.26, 95% CI = 1.07–1.49) and fatigue (CRP OR = 1.12, 95% CI = 1.04–1.21; IL-6 OR = 1.19, 95% CI = 1.07–1.33)." (PMID 34135474, 2021). "Findings of increased CRP levels and IL-6 overactivity with other PHQ-9 symptoms were inconsistent, but there were some indications that IL-6 signaling could be associated with hypersomnia, which requires replication in future work." (PMID 33079133, 2021). "More attention should be paid when patients exhibit hypersomnia, convulsions, stiff neck, vomiting, limb shaking, hyperarousal, fever, breathlessness and certain laboratory parameters (IL-6 levels, CD4+ levels, neutrophil ratio and lymphocyte ratio) which could reduce the intensification of HFMD." (PMID 35482791, 2022). "Only hypersomnia, but not loss of sleep, showed consistent associations with CRP and IL-6." (PMID 34135474, 2021).
Hypocholesterolemia (6 papers, 2021 to 2025). An decreased concentration of cholesterol in the blood. "Increased levels of cytokines such as IL-6 and activation of NF-kB associated with increased inflammation because of proliferation of tumor cells can cause hypocholesterolemia." (PMID 35967813, 2022). "Circulating NETs were detected in 61 patients (28.8%) and higher NETs levels were significantly associated with elevated D-dimer, LDH, IL-6, PCT, and hypocholesterolemia." (PMID 41229414, 2025). "Higher expression of NR4A1 is observed in leukocytes from patients with hypocholesterolemia and in cell culture cholesterol induces NR4A1 and loss of the receptor enhances expression of inflammatory genes such as IL-6 and MCP-1." (PMID 40871737, 2025).
Hypokalemia (6 papers, 2020 to 2025). An abnormally decreased potassium concentration in the blood. "Additionally, prolonged hypokalemia affects the proliferation and differentiation of T cells and monocyte-macrophages, as well as the expression of pro-inflammatory cytokines such as IL-1β, IL-6, and TNF-α." (PMID 40783707, 2025).
hypophosphatemia (6 papers, 2020 to 2024). Lower than normal levels of phosphates in the circulating blood. "Hypophosphatemia was associated with higher values of IL6 (p = 0.044) and need for inotropic support (p = 0.05)." (PMID 37892324, 2023). "High levels of pyrogenic proinflammatory cytokines, such as tumour necrosis factor (TNF) and interleukin-6 (IL-6) have been correlated with hypophosphatemia, and can induce hypophosphatemia when administered experimentally." (PMID 32085712, 2020). "In our study, we found that low levels of serum phosphate seem to be not related to tubular dysfunction but more probably to the inflammatory state and a more severe course, given the positive correlation of hypophosphatemia with higher serum levels of IL-6 and use of inotropes." (PMID 37892324, 2023).
Hypothermia (6 papers, 2009 to 2023). Reduced body temperature due to failed thermoregulation. "Hypothermia was associated with a reduction in: (i) immune cell infiltration, (ii) apoptosis, (iii) IL-1β and IL-6 mRNA up-regulation, and (iv) IL-1β protein expression (p<0.05)." (PMID 19855846, 2009). "Hypothermia can lower brain metabolism and cerebral blood flow while reducing pro-inflammatory factors like IL-6 and TNF-α." (PMID 38178890, 2023). "Hypothermia has been found to decrease inflammation by decreasing both the infiltration of polymorphonuclear cells and the production of a wide range of inflammatory proteins such as TNF-α, IL-1b, IL-6, and macrophage inflammatory protein-2." (PMID 27583464, 2016). "Hypothermia and locomotor hypoactivity were induced by LPS>IL-1β>TNF-α>>IL-6." (PMID 23840908, 2013).
idiopathic pulmonary arterial hypertension (6 papers, 2015 to 2024). A sporadic form of pulmonary arterial hypertension (PAH) characterized by elevated pulmonary arterial resistance leading to right heart failure. "The increase in IL-6 levels can be influenced by the IL-6 -572 gene polymorphism, idiopathic pulmonary arterial hypertension, DVT, and the interaction of the IL-6 gene promoter haplotype." (PMID 37239434, 2023).
imbalance (6 papers, 2017 to 2025). "Among the PwP, changes in plasma EV-derived IL-1β, TNF-α and IL-6 levels were significantly associated with changes in the severity of postural instability and gait disturbance (PIGD) and cognition." (PMID 36897204, 2023). "This immune imbalance is similarly implicated in the development of DeP, where chronic inflammation and excessive inflammatory responses release pro-inflammatory cytokines (e.g., IL-6, TNF-α) that affect the central nervous system." (PMID 41212883, 2025). "This study demonstrates that maternal immune imbalance in late pregnancy—particularly an elevated IL-6/IL-10 ratio—acts as a biologically relevant determinant of fetal telomere shortening, independent of common clinical risk factors." (PMID 40868226, 2025). "APS can efficiently inhibit Cd-induced immune imbalance in chicken PBLs through the regulation of MDA5/NF-κB signaling, and it can decrease Cd-induced expression of cytokines (IL-1β, IL-6, and TNF-α)." (PMID 28946702, 2017).
Jaundice (6 papers, 2014 to 2022). Yellow pigmentation of the skin due to bilirubin, which in turn is the result of increased bilirubin concentration in the bloodstream. "Breastmilk jaundice may occur due to certain factors present in human breastmilk (i.e., IL 1ß, IL6, ß-glucuronidase, epidermal growth factor, alpha-fetoprotein), which inhibits the conjugation of bilirubin that facilitates its excretion." (PMID 31440488, 2019).
limb ischemia (6 papers, 2017 to 2025). A ischemia that involves the limb. "Clinical stratification revealed significantly higher IL-6 concentrations in patients with Severe Limb Ischemia compared to those presenting with claudication alone, establishing a quantitative relationship between cytokine levels and disease severity." (PMID 40776916, 2025). "The significantly high levels of IL-6, TNF-α, MDA, and the increase of PMNs in lung tissues in group IR support the notion that the systemic inflammatory response and lipid peroxidation may be involved in mechanisms concerning pulmonary dysfunction after limb ischemia/reperfusion." (PMID 28629353, 2017).
lumbar disc degeneration (6 papers, 2017 to 2025). "The G allele has been shown to enhance IL6 gene expression and increase plasma IL-6 levels in response to stress stimuli, and has been previously associated with Achilles’s tendinopathy, lumbar disc degeneration, and power/strength athlete status." (PMID 41300761, 2025). "Background/Objectives: The aim of the study is to investigate the role of microRNA-17 (miRNA-17), tumor necrosis factor-alpha (TNF-α), and interleukin-6 (IL-6) in the pathogenesis of lumbar degenerative disc disease (LDDD)." (PMID 40095903, 2025). "IL-6, an important mediator of immune responses and inflammation in the interleukin family, also plays an important role in the process of lumbar disc degeneration." (PMID 35096205, 2022). "IL6 variants have not been studied related to the surgical outcome of DDD yet but they were previously associated with the process of lumbar disc degeneration." (PMID 35964023, 2022). "In conclusion, this study preliminarily indicated the relationship between IL-6 and TNF-α and the severity of lumbar disc degeneration." (PMID 35096205, 2022).
monoclonal gammopathy (6 papers, 2019 to 2025). A condition characterized by the abnormal presence of monoclonal immunoglobulins in the blood or urine. "A correlation between serum concentrations of IL-6 and the different status of monoclonal gammopathies has been reported by several works." (PMID 31185596, 2019). "For instance, pro-inflammatory cytokines such as interleukin-6 (IL-6) and tumor necrosis factor-alpha (TNF-α) promote plasma cell survival and proliferation, potentially contributing to the establishment of monoclonal gammopathy." (PMID 40824475, 2025).